SOX10 (SRY-box transcription factor 10)
Diseases named in the same sentence as SOX10 in open-access papers (continued):
Sharing a sentence is not in itself a finding about the gene and the disease.
tumor (continued). "CMTM7 knockdown promotes tumor growth, whereas SOX10-dependent CMTM7 overexpression decreases the cancer cell proliferation rate, thus slowing tumor growth." (PMID 32944388, 2020). "Immunohistochemical studies demonstrated that negativity of SMA, desmin, β-catenin, S100, SOX10, AE1/3, EMA, CD117 and CD34 in the tumor cells." (PMID 32164724, 2020). "In summary, we demonstrate in a large NSCLC tumor tissue cohort that expression of HMB45, MelanA, and SOX10 is exceedingly rare in NSCLC cases and almost restricted to tumors with squamous differentiation." (PMID 30205833, 2018). "In the mouse xenograft model, SOX10 knockdown also blocked FOXD3/ERBB3 induction by Vemurafenib, reduced tumor growth and further enhanced the tumor-inhibiting capacity of Vemurafenib." (PMID 29295999, 2018). "Immunohistochemical studies confirmed the tumor cells to be immunoreactive with cytokeratin AE1/3, cytokeratin 5/6, cytokeratin 7, p63, and SOX10." (PMID 29651355, 2018). "Immunohistochemically, the tumor cells were strongly positive for CK7, EMA, vimentin, SOX10, S-100, and focally positive for CA9." (PMID 29041930, 2017). "SOX10 and TRF2 and SOX10 were expressed in the nuclei, whereas CD10 was mainly expressed at the tumor cell membrane." (PMID 26945789, 2016). "Conversely the intensity of SOX10, CD10 and TRF2 immunostaining was heterogeneous, depending on the tumor." (PMID 26945789, 2016). "Immunohistochemically, the tumor cells were positive for CK19, S100, SOX10, and Mammaglobin." (PMID 42294308, 2026). "In the example of melanoma, high SOX10 levels co-staining with DNA identify tumor cells, whereas CD3D forming a circle around a cell indicates the boundaries of a cell with the potential for tumor-cell killing." (PMID 39255170, 2025). "On March 28, 2024, pathological examination revealed tumor cells negative for P16, SOX10, S100, and H3K27me3, indicating potential malignancy." (PMID 40630199, 2025). "Immunohistochemistry showed that tumor cells were S100+, CD34+, SOX10+, c-kit−, desmin−, DOG1−, ER−, HMB45−, STAT6−, Oct4−, synaptophysin−, AE1/AE3−, SMA−, and vimentin+; for a small fraction of cells, EMA+, synaptophysin−, BCL2−, and β-catenin− and MIB-1 positivity was about 1%." (PMID 40777560, 2025). "All tumours were strongly and diffusely positive for S100 (nuclear and cytoplasmic), Sox10 (nuclear), MelanA (cytoplasmic) and negative for HMB45, except for a junctional component in the conventional background naevi." (PMID 39268598, 2025). "In the control group, GFP+ tumor cells exhibited high expression of OLIG2 but lacked the expression of the oligodendrocyte marker SOX10." (PMID 40428395, 2025). "While simple correlative analysis of CD8+ T cells and SOX10+ tumor cells did not reveal significant changes, it is notable that those two populations were mainly dispersed in the TME at baseline." (PMID 41282765, 2025). "Conversely, GFP+ cells in Olig1/2F/F; H2bF/+ mice showed no co-labeling with OLIG2 or SOX10, confirming that the deletion of Olig1/2 in tumor cells did not alter the astrocytic GBM cell phenotype." (PMID 40428395, 2025). "For instance, although Patient 1 lacked a normal FFPE or fresh-frozen biopsy as a germline control, isolating diploid, SOX10-negative cells from the bulk tumor tissue using FACS allowed us to recover the non-tumoral cell population from the tumor sample." (PMID 40004220, 2025). "Immunohistochemical stains demonstrated positivity of the tumor with sex-determining region Y-box 10 (SOX10) and negative staining with smooth muscle actin (SMA), Cluster of Differentiation 10 (CD10), protein 40 (P40), cytokeratin 5/6 (CK5/6), and melanin." (PMID 40125165, 2025). "Tumor cells often demonstrate positivity for S100 and SOX10 while they are consistently negative for calponin and mammaglobin." (PMID 40176070, 2025).
tumor (continued). "In ER‐negative EPC‐like tumours with high nuclear grade, high mitotic activity, and no peripheral MEC layer, it is helpful to perform GATA3 and SOX10 IHC to support primary breast origin as metastatic tumours with papillary morphology should be excluded." (PMID 39209705, 2025). "In our case, the tumor showed positivity for S100 and SOX10 but was negative for common melanocytic markers such as HMB-45, Melan-A, and PRAME." (PMID 40636637, 2025). "Tumour cells stained HMB‐45, Melan‐A, and SOX10 positive, AE1/AE3 negative, and carried an NRAS‐Q61 mutation with wild‐type BRAF, confirming cutaneous origin." (PMID 40918809, 2025). "Collectively, SOX10 may inhibit the killing effect of immune cells on SKCM and promote tumor immune escape by inhibiting immune cell infiltration and IFN-γ/JAK/STAT signaling pathway." (PMID 40342816, 2025). "On immunohistochemical (IHC) staining, tumor cells showed patchy expression of CD56, but the tumor was negative for broad-spectrum keratins, PAX8, TTF1, thyroglobulin, calcitonin, HBME-3, CEA, PTH, GATA3, p63, SOX10, and S-100." (PMID 40277780, 2025). "Immunohistochemical staining revealed that the tumor cells were positive for S100 protein, H3K27me3, and SOX-10 but negative for CD34 and MIB-1 index of 5%, indicating no malignancy." (PMID 40861330, 2025). "For example, both superficial and deep MRs from MEL18 and MEL25 contained neighboring tumor cells expressing SOX9, SOX10 and MART1 in different combinations and intensities, consistent with frequent changes in molecular programs associated with these melanocyte markers." (PMID 40667360, 2025). "Consequently, low SOX10 expression leads to a low MITF expression, retaining the tumor in the mesenchymal phenotype." (PMID 40458894, 2025). "He underwent a thoracoscopic biopsy of the large tumor and was histopathologically diagnosed with a benign schwannoma that was immunohistochemically positive for S100 protein, H3K27me3, and SOX-10, and negative for an MIB-1 index of <5%." (PMID 40861330, 2025). "By immunohistochemistry, the tumor cells were positive for SOX10, S100, p63 and negative for p40, calponin and mammaglobin." (PMID 40176070, 2025). "Immunohistochemically, the tumor was positive for S-100, Melan A, HMB-45, and SOX-10." (PMID 41001300, 2025). "An immunohistochemical (IHC) study was performed in order to confirm the histogenesis of the tumor using an automatic Bond immunostainer with the antibodies CK7, CK20, p63, and SOX10 on serial sections from the paraffin block using control sections to assess the reaction." (PMID 41375883, 2025). "In contrast, although SOX2 and SOX10 showed positive immunostaining, they did not exhibit statistically significant correlations with histopathological indicators of tumor aggressiveness." (PMID 41012776, 2025). "Only tumor SP‐01 presented strong dual staining for S100B and SOX10, contrary to classic MPNSTs that present negative or focal expression, like S100B expression in the SP‐04 tumor." (PMID 37798904, 2024). "In the RGNT samples, compared with the non-tumour regions, strong stainings of OLIG2, SOX10, NG2 and PDGFRA were observed in the neurocytic regions in all samples analysed, and the astrocytic regions of the same samples showed sporadic and weaker expression of OLIG2, SOX10, NG2 and PDGFRA." (PMID 38764775, 2024). "The proportion of positive SOX10 expression was significantly higher in tru-cut biopsies and in tumors with the absence of tumor-infiltrating lymphocytes." (PMID 38813332, 2024). "The tumour cells showed diffuse immunoreactivity for S-100 and SOX10 proteins, but no immunostaining was observed for smooth muscle actin (alpha-SMA) and KIT (CD117)." (PMID 38201647, 2024).
tumor (continued). "The tumour cells were positive for the SOX10, S100, and p63 protein and negative for the p40 protein according to immunohistochemistry." (PMID 38982505, 2024). "By immunohistochemistry, the tumor cells showed diffuse S100 and SOX10 positivity, while luminal DOG1 staining without a cytoplasmic reaction was also observed in this case." (PMID 39101978, 2024). "SOX10, a transcription factor expressed by migratory NC cells, has been shown to be highly expressed by melanoma cells and required for tumor formation, while SOX9, a NC specifier, rather regulates tumor invasion." (PMID 38282579, 2024). "However, we found that tumor BCAS1+ cells express other oligodendroglial markers (i.e., OLIG2 and SOX10) related to immature stages within the oligodendrocyte linage." (PMID 38275289, 2024). "This discrepancy was also observed within control tumors but in the opposite direction, whereby many SOX10+ tumor cells are negative for OLIG2." (PMID 39609428, 2024). "This was revealed by ASCL1’s ability to promote an increase in early migration of newly transformed GFP+ tumor cells out of the SVZ at P4 into the striatum, corpus callosum, and cortical plate of Ascl1-OE mice prior to their specification into either GFAP+ or SOX10+ tumor cells." (PMID 39609428, 2024). "Notably, terminal control tumors exhibited a much higher percentage of SOX10+ cells (~90%) than OLIG2+ cells (61%), whereby SOX10 was observed in a subset of OLIG2-;tdTOM+ tumor cells." (PMID 39609428, 2024). "All breast-specific markers including SOX10, GATA3, mammoglobin, and GCDFP15, expressing positively at the primary tumor site, may lose their expression at the metastatic site and vice versa." (PMID 38813332, 2024). "The positive correlation of SOX10 immunohistochemical expression with tru-cut biopsy samples and the negative correlation with tumor-infiltrating lymphocytes point towards possible roles of proper tissue fixation and host immunity in its expression." (PMID 38813332, 2024). "In contrast, our findings show nearly universal staining of pan-oligodendrocyte lineage markers OLIG2 and SOX10, OPC makers PDGFRA and NG2 and developing oligodendrocyte marker Nogo-A in the tumour cells of DNET, MGNT and RGNT samples and an enrichment of OPC signature in DNET transcriptomes." (PMID 38764775, 2024). "In the right ankle tumor, S100 and SOX-10 were diffusely positive in spindle tumor cells, while HMB45 and Melan-A were negative." (PMID 37352079, 2023). "This is, however, a very time-consuming and difficult task when tumor cells frequently are SOX10 negative." (PMID 36361209, 2022). "The overlapping expressions of SOX10 and DEPDC1B in patient samples and in the tumor nodules prompted us to investigate whether SOX10 regulates DEPDC1B expression." (PMID 35088579, 2022). "The tumor cells showed positive staining for the expression of pan-cytokeratin (AE1/AE3), S-100, brachyury, and SOX9 but negative staining for the expression of calretinin, D2-40, KIT, CD34, DOG-1, desmin, alpha-SMA, Melan-A, HMB45, and SOX10." (PMID 35398781, 2022). "As anticipated, recurred tumours from DMSO controls lacked mCherry signal in Sox10+ and Mitfa+ tumour cells (B′)." (PMID 35929478, 2022). "A few tumor cells resided in a neural crest-like state, as identified by co-localized SOX11 and TFAP2B regulon activities, and exhibited a low level of melanocytic regulon activity compared to intermediate, except for SOX10." (PMID 35903095, 2022). "Immunoperoxidase stains were performed on a Ventana NEXES Automated Immunohistochemistry System (Fuzhou Maixin Biotech Co., Ltd., Fuzhou, China) Vimentint, HMB45 and Melan A were positive in the tumor cells, while CKp, S-100, SOX-10, and CD68 were negative." (PMID 36686734, 2022).
tumor (continued). "According to the tumor grade, SOX10 staining was classified as negative (<1%), patchy (1-10%), focal (10-70%), and diffuse (70-100%)." (PMID 36120242, 2022). "SOX10 has been shown to be expressed in virtually all BPNST; however, there are several reports identifying the absence of SOX10 staining in MPNST in 30% of tumours, which can be problematic for pathologists in diagnosing malignant spindle cell lesions." (PMID 35323240, 2022). "In metastases, a high number of SOX10-negative tumor cells was observed in lymph-node and organ metastases." (PMID 36361209, 2022). "With the increasing grade of conventional MNSTs, we recorded a slight decrease in the expression of IHC markers Sox10, claudin-1, and GFAP, which could be the result of poorer differentiation of tumor cells in higher-grade tumors." (PMID 35622732, 2022). "For this case, a NST diagnosis was excluded based on lack of LAM and PXN; however, the tumor expressed Sox-10 and SMA." (PMID 36669002, 2022). "We found that Pan-TRK, S-100, and CD34 were positive by IHC analysis, while SOX10 and desmin were negative in the tumor." (PMID 35572973, 2022). "Immunohistochemistry, the tumor cells were diffusely positive for S-100 protein, SOX-10 and CD68, while they were completely negative for desmin, DOG-1, AE1/AE3 and P63." (PMID 34243786, 2021). "Furthermore, immunohistochemistry analysis revealed that tumor cells were positive for S-100 protein, HMB-45, Melan-A, and SOX10." (PMID 33478436, 2021). "SOX2 staining was specific to GBM cells, as the vast majority of endogenous SOX10+ OPCs were negative for SOX2 in areas of tumour infiltration." (PMID 33846316, 2021). "The tumor cells were diffusely positive for S-100 protein, SOX-10 and CD68, while they were completely negative for desmin, DOG-1, AE1/AE3 and P63." (PMID 34243786, 2021). "In addition, SOX10+ cells were lowly proliferative, progressed to a CNP+/CC1+/MBP− immature pre-oligodendrocyte state and were restricted to MBP+ tumour regions." (PMID 33846316, 2021). "This was not an artefact of SOX10 overexpression, as O4+ tumour cells acutely FACS-purified from the corpus callosum of wildtype G144 xenografts were also significantly less motile than O4- cells from the same region." (PMID 33846316, 2021). "Notably, in PDX1214 the SOX10 expression pattern matched well with the CD40 expression pattern based upon IHC staining, even though there was only minimal inhibition of tumor growth." (PMID 34092233, 2021). "Additionally, we performed immunohistochemical staining for SOX10, CD3, CD4, CD8, BCL2, and caspase-3 in lgCMN tissues to detect the tumor-infiltrating lymphocytes (TILs) and antiapoptotic phenomenon." (PMID 34912899, 2021). "Tumor cells were diffusely positive for CK7, S100 protein, SOX10, and mammaglobin." (PMID 33237469, 2021). "For this purpose, and based on the expression or absence of tumor markers (e.g., cytokeratin and SOX10/S100), we can divide the image into tumor cell nests and the stromal compartment." (PMID 33996912, 2021). "Tumors from both models were indistinguishable, both containing high numbers of Tomato+ tumor cells expressing both S100b and Sox10, which was expected as Tyr and c-Kit promoters targets the same population of McSCs in the hair follicle." (PMID 31685822, 2019). "Indeed the notion of tumor cell subpopulations is yet deeply investigated at the single-cell level and markers such as MITF or SOX10 have been suggested to identify them." (PMID 31118886, 2019). "In a total of 1027 NSCLC tumor tissue specimen HMB45, MelanA, SOX10, CK5/6, NapsinA, p63, and TTF-1 could be evaluated." (PMID 30205833, 2018). "The metastasis which was resected in February 2014 was highly necrotic with some areas of viable tumor as evident by SOX10 staining, whereas no necrosis was seen in the metastasis that was removed in August 2014." (PMID 28716097, 2017).
tumor (continued). "Immunohistochemically, the tumor cells showed strong cytoplasmic expression for CK7, S-100, vimentin, EMA, nuclear expression for SOX10, focal membranous for CA9, and were negative for thyroglobulin, actin, calponin, PAX8, CD10, CK20, CDX2, CD117, DOG-1 and SMA." (PMID 29041930, 2017). "SOX10 turned from positive to negative in patient No. 1 as treatment started, and also in patient No. 6 as signs of spontaneous tumor regression were seen on CT scans." (PMID 27110718, 2016). "Conversely, TRF2, CD10, and SOX10 expression was weak or absent in iCTCs (Fig. 2B1, C1 and D1), whereas most of the tumor cells forming the CTMs strongly expressed these three markers (Fig. 2B2, C2 and D2)." (PMID 26945789, 2016). "Six paired patient tumor biopsies were examined for pERK, PD1, TUNNEL, SOX10, and MART1." (PMID 27748045, 2016). "Finally, the clinical implications were investigated by comparing the expression profiles of SOX5, SOX10 and MITF to clinically relevant parameters (overall survival and tumor stage), leading to a biomarker regression model (of SOX5, SOX10 and MITF)." (PMID 26927636, 2016). "GFP expression was variable; some areas of the tumor showed strong expression of GFP, but spindle-like tumor cells showed very weak or almost negative expression of GFP, likely caused by loss of sox10 promoter activity in fully differentiated cells." (PMID 27655644, 2016). "The differential diagnosis for Triton tumor was dismissed by immunohistochemical analysis that showed negative staining for Sox10, S-100 and findings of abdominal CT." (PMID 26208724, 2015). "Furthermore, we found that SOX10 inhibited the EMT and stemness of tumor cells and their migration and invasion through antagonizing Wnt/β-catenin signaling." (PMID 25301735, 2014). "Given that SOX10 inhibits cancer metastasis, we wonder whether SOX10 plays a role in regulating epithelial-mesenchymal transition (EMT), a critical event in tumor invasion." (PMID 25301735, 2014). "We found that SOX10 protein was normally expressed in paired non-cancerous colorectal, gastric and esophageal tissues, whereas it was hardly or weakly detected in tumor tissues." (PMID 25301735, 2014). "Tumor cells of EMPNST are tightly arranged in the form of thick beams, nodules, or nests, with abundant eosinophilic cytoplasm, obvious nucleoli, and immunophenotypically diffusely positive for S-100 and SOX-10, with expression of CK-pan and retained positivity for H3K27me3." (PMID 40432917, 2025). "Notably, the tumor cells were consistently immunopositive for S100 and SOX10 as well as CK7, whereas p40 was completely negative in all cases tested and p63 exhibited only scattered positivity in 8/25 cases (32%) and diffuse positivity in 1/25 cases (4%)." (PMID 40033554, 2025). "Therefore, the tumor location, the cellular morphology observed in microscopy, and the negative results for markers such as S100, SOX10, CD45, and C35 further guide the PSCC diagnosis and rule out other cellular origins of malignancy." (PMID 40026987, 2025). "Immunohistochemistry revealed that the tumour cells were positive for vimentin and SMA expression, focal expression of calponin and CD10, and weak expression of β-catenin, with no expression of CD117, DOG-1, desmin, caldesmon, HMB45, ALK, CD34, S-100, CK, or SOX10." (PMID 41357577, 2025). "Among the SOX family proteins studied, the SOX3 protein plays a role in the regulation of cell proliferation in oral melanomas, and it is suggested that the SOX2 and SOX10 proteins are constitutively expressed in these neoplasms, without a determining role for aggressiveness." (PMID 41012776, 2025). "However, there is currently a lack of evidence for the regulation between SOX10 and NK cells, and their roles in tumor initiation and progression." (PMID 40342816, 2025). "The tumor cells expressed Sox-10 and S100, but were negative for Melan-A." (PMID 40290795, 2025).